LINC00472 (long independently transcribed non-coding RNA 472)
Synonyms: C6orf155; PEXF; P53RRA; FLJ13189; dJ288M22.3
Gene: Long non-coding RNA gene on chromosome 6 (71,187,161 to 71,420,745, reverse strand). Ensembl gene ENSG00000233237.
Gene Ontology:
Biological process: miRNA-mediated post-transcriptional gene silencing
Cellular component: RISC complex
Diseases named in the same sentence as LINC00472 in open-access papers:
LINC00472 is named in the same sentence as 22 diseases in open-access papers, as found by Europe PMC text mining. Sharing a sentence is not in itself a finding about the gene and the disease. The quoted sentences say what the papers report.
breast carcinoma (7 papers, 2015 to 2022). "For example, Neat1, which is overexpressed in advanced ovarian carcinoma and assists diagnosis, and LINC00472, high expression of which is correlated with reduced risk of relapse and death of breast cancer patients." (PMID 27485121, 2016). "In addition, a former study reported that LINC00472 over-expression significantly decreases the risk of relapse in patients with breast cancer, and LINC00472 also inhibits breast cancer cell proliferation and migration." (PMID 28793054, 2017). "LINC00472 is initially identified as a prognostic biomarker in breast carcinoma, and a highly expressed LINC00472 predicts excellent disease outcomes." (PMID 35258410, 2022). "Collectively, our clinical and in vitro studies suggest that LINC00472 is a tumor suppressor in breast cancer." (PMID 25865225, 2015). "Downstream from the LINC00472 gene, there are two microRNA genes, miR30c and miR30a, which have been reported to have possible effects on breast cancer invasion, metastasis and patient response to chemotherapy." (PMID 25865225, 2015). "We notice that the deletion of this gene is rare in the TCGA data, and therefore the low expression of LINC00472 in breast cancer is likely due to the down-regulation of expression." (PMID 25865225, 2015). "MiR-200c-3p, miR-204-5p, miR-20b-5p, miR-7-1-3p, miR-105-5p, miR-342-3p, DNMBP-AS1, HPN-AS1, LINC00461, LINC00472, LINC00667, LOC100128164, LOC284578, MESTIT1, RHPN1-AS1, and SLC26A4-AS1 were significantly associated with breast cancer patients’ overall survival (log-rank P < 0.05)." (PMID 34220926, 2021). "A previous study reported that low Linc00472 expression led to poor prognosis in breast cancer." (PMID 29930217, 2018). "Using GEO2R, an interactive web tool in GEO, we analyzed the relationships of LINC00472 expression and breast cancer characteristics in multiple GEO datasets generated from the most recent microarray chips, the Affymetrix Human Genome U133 plus 2.0 array and the U133A array." (PMID 25865225, 2015). "For example, LINC00472 has shown a low expression level in NSCLC, breast cancer, ovarian cancer, hepatocellular carcinoma, and osteosarcoma." (PMID 35258410, 2022). "We found that in the regulatory network, miR-301a-3p, miR-93-5p, miR-454-3p, miR-181b-5p, XIST, LINC00472, MIR31HG, MEG3, MIR155HG, and LINC00667 have been reported in breast cancer." (PMID 34220926, 2021).
colorectal cancer (3 papers, 2018 to 2022). A primary or metastatic malignant neoplasm that affects the colon or rectum. "Elevated Linc00472 expression suppressed proliferation and induced apoptosis in colorectal cancer cells." (PMID 29930217, 2018). "Furthermore, miR-196a overexpression or PDCD4 knockdown reversed Linc00472-mediated proliferation inhibition and apoptosis induction in colorectal cancer cells." (PMID 29930217, 2018). "In this study, we found that Linc00472 was down-regulated in colorectal cancer tissues and cells." (PMID 29930217, 2018). "Similarly, LINC00472 was found to promote cell apoptosis and suppresses cell proliferation through elevating PDCD4 expression by sponging miR-196a in colorectal cancer." (PMID 36371410, 2022). "However, the function and mechanism of Linc00472 in colorectal cancer has not been well elucidated." (PMID 29930217, 2018).
lung adenocarcinoma (3 papers, 2019 to 2024). A carcinoma that arises from the lung and is characterized by the presence of malignant glandular epithelial cells. "In conclusion, LINC00472, which is lowly expressed in lung adenocarcinoma tissue, changes the biophysical properties of cells and inhibits the migration and invasion of lung adenocarcinoma cells by binding to YBX1." (PMID 33144579, 2020). "LINC00472 expression was also low in lung adenocarcinoma tissues compared to noncancerous lung epithelium tissues according to the GEO database (GSE27262 and GSE31210)." (PMID 33144579, 2020).
lung carcinoma (3 papers, 2020 to 2022). "Several studies have demonstrated LINC00472 as a tumor suppressor (for instance lung cancer, osteosarcoma, and hepatocellular carcinoma)." (PMID 35258410, 2022). "LINC00472 is reported to play a role in suppressing tumors in cancers such as lung cancer and hepatocellular carcinoma, among others." (PMID 35258410, 2022).
ovarian carcinoma (3 papers, 2018 to 2022). A malignant neoplasm originating from the surface ovarian epithelium. "The tumour‐suppressive role of LINC00472 has been extensively reported in various human cancers such as lung, colon and ovarian cancers, yet its function in pancreatic cancer remains unidentified." (PMID 34363438, 2021).
pancreatic cancer (2 papers, 2021 to 2023). "The results showed that miR‐23a‐3p was up‐regulated in the pancreatic cancer tissues, while the miR‐23a‐3p expression pattern was negatively correlated with the LINC00472 expression pattern." (PMID 34363438, 2021). "In this study, we constructed both cellular and animal models to systematically investigate the signalling axis ZEB1/LINC00472/miR‐23a‐3p/FOXO3 in pancreatic cancer." (PMID 34363438, 2021). "Linc00472 serves as a tumor suppressor in colorectal and pancreatic cancers." (PMID 37958599, 2023). "Linc00472 is a tumor suppressor in colorectal and pancreatic cancers." (PMID 37958599, 2023). "In order to determine whether ZEB1 can regulate the expression pattern of LINC00472 in the progression of pancreatic cancer, we further examined the expression pattern of ZEB1 in the pancreatic cancer tissues and adjacent normal tissues by RT‐qPCR." (PMID 34363438, 2021). "Consequently, LINC00472 silencing resulted in facilitated tumorigenicity of pancreatic cancer cells in vivo, reduced expression pattern of Ki‐67 and suppressed cell apoptosis." (PMID 34363438, 2021). "To conclude, our data presented that LINC00472, a lncRNA down‐regulated by ZEB1 in pancreatic cancer, could function as tumour suppressor in pancreatic cancer, thus establishing the significance of LINC00472 as a therapeutic target against pancreatic cancer." (PMID 34363438, 2021). "The obtained miRNAs were intersected with the up‐regulated miRNAs in the GSE24279 data set, the results of which identified that miR‐23a‐3p could independently bind to LINC00472, and moreover, miR‐23a‐3p was highly expressed in pancreatic cancer." (PMID 34363438, 2021). "Therefore, we speculated that LINC00472 may regulate the expression pattern of BID through FOXO3 to subsequently manipulate the development of pancreatic cancer." (PMID 34363438, 2021). "Therefore, we speculated that LINC00472 may regulate the development of pancreatic cancer through miR‐23a‐3p." (PMID 34363438, 2021). "In summary, the preceding results indicated that silencing of LINC00472 inhibited the expression pattern of BID through miR‐23a‐3p/FOXO3 to promote the proliferation and inhibit the apoptosis of pancreatic cancer cells." (PMID 34363438, 2021). "Such regulatory axis was verified in both in vitro and in vivo settings, and our data demonstrated that LINC00472 silencing had fundamentally suppressed BID expression through miR‐23a‐3p‐mediated inhibition of FOXO3 to promote proliferation and inhibit the apoptosis of pancreatic cancer cells." (PMID 34363438, 2021).
atherosclerosis (1 paper, 2021). A disease characterized by the build-up of fatty material and calcium deposition in the arterial wall resulting in partial or complete occlusion of the arterial lumen. "Additionally, upregulated LINC00472 increases the migration rate of VSMCs in atherosclerosis by regulating miR-149-3p." (PMID 34987381, 2021).
bladder tumor (1 paper, 2021).
breast tumors (1 paper, 2024). "LINC00472 as a tumor suppressor gene, the high expression of LINC00472 in less aggressive breast tumors is more conducive to the prognosis of patients and also has a good response to adjuvant chemo- or hormonal therapy." (PMID 38978021, 2024).
pterygium (1 paper, 2020). A wedge-shaped fibrovascular lesion arising from the bulbar conjunctiva and extending to the cornea. "In addition, the mRNAs in both networks are enriched in PID FOXM1 PATHWAY, indicating that LINC00472 is likely to regulate the growth of pterygium through PID FOXM1 PATHWAY." (PMID 33299863, 2020). "We presume that the LINC00472 network might function in pterygium via the FOXM1 PATHWAY, especially through the regulation of CCNB1, MYC, ERBB4, RELN, RB1, and CDH2 in the ceRNA network." (PMID 33299863, 2020).
Sepsis (1 paper, 2021). Sepsis is defined as life-threatening organ dysfunction caused by a dysregulated host response to infection. "Expression levels of LINC00472 were found to be higher in rats with sepsis-induced AHI, relative to control group rats." (PMID 34987381, 2021). "Negative regulation of LINC00472 and TRIM8 as well as positive regulation of miR-373-3p improves cell viability and accelerates cell apoptosis, thereby alleviating sepsis-induced AHI." (PMID 34987381, 2021).
triple-negative breast carcinoma (1 paper, 2023). An invasive breast carcinoma which is negative for expression of estrogen receptor (ER), progesterone receptor (PR), and human epidermal growth factor receptor 2 (HER2). "LINC00472 is down-expressed in patients with triple-negative breast cancer and is significantly associated with poor pathological differentiation, lymph node metastasis, and clinical grade." (PMID 37901333, 2023). "LINC00472 plays a tumor suppressor role in triple-negative breast cancer." (PMID 37901333, 2023).
tumor (11 papers, 2015 to 2024). "For instance, LINC00472 has been recognized to serve as a tumor suppressor in BC in association with the survival time of patients." (PMID 33668040, 2021). "LINC00472 expressions in epithelial OC have been associated with disease stage and tumor grade." (PMID 34987381, 2021). "This knowledge of LINC00472 function and its tumor regulating mechanism highlights its potential as a target for treating OSCC." (PMID 35258410, 2022). "In conclusion, LINC00472 was identified as a suppressor of OSCC tumor cell proliferation and in vivo tumor growth." (PMID 35258410, 2022). "Although reports on LINC00472 are limited in non-tumor disease, the current evidence suggests that LINC00472 is a potential marker and a promising target for cancer diagnosis/prognosis and therapy." (PMID 34987381, 2021). "Meanwhile, the inhibitory role of LINC00472 in tumorigenesis was validated in vivo, and the LINC00472‐mediated miR‐23a‐3p/FOXO3/BID axis was also demonstrated in the nude mouse tumour formation model." (PMID 34363438, 2021). "Overexpressed LINC00472 was shown to suppress the oncogenic properties of TNBC cells in vitro while suppressing tumor growth in vivo by down-regulating MCM6 and blocking the MEK/ERK signaling pathway, implying that MEK/ERK is a possible target of LINC00472." (PMID 34987381, 2021). "Several existing studies indicate that LINC00472 plays an important role in inhibiting tumor development." (PMID 30755833, 2019). "Functional analysis revealed that Linc00472 overexpression inhibited proliferation and enhanced apoptosis in vitro and hindered tumor growth in vivo in CRC." (PMID 29930217, 2018). "Mechanically, Linc00472 acted as a tumor suppressor in CRC by up-regulating PDCD4 via sponging miR-196a." (PMID 29930217, 2018). "Linc00472 overexpression hindered tumor growth in nude mice, evidenced by suppressed tumor volume and weight." (PMID 29930217, 2018). "In the present study, we found that Linc00472 was significantly down-regulated in CRC tumor tissues compared with normal tissues from our samples and TCGA data." (PMID 29930217, 2018). "The results show that miR-455-3p/ELF3 mediates the anti-tumor function of LINC00472 in OSCC." (PMID 35258410, 2022). "The role that LINC00472 plays in OSCC tumor growth was examined by establishing a xenograft model." (PMID 35258410, 2022). "As a tumor suppressor, LINC00472 suppresses cell proliferation, migration as well as invasion." (PMID 34987381, 2021). "Over a series of gain-of-function and rescue experiments, the results revealed that the methylation-dependent repression of MCM6 due to LINC00472 mediation was the potential mechanism substantiating the anti-tumor and anti-metastatic properties of LINC00472 in TNBC." (PMID 33668040, 2021). "Moreover, Linc00472 acted as a tumor suppressor by sponging miR-196a and releasing PDCD4." (PMID 29930217, 2018). "All these studies suggested that Linc00472 may act as a tumor suppressor in cancers." (PMID 29930217, 2018). "More importantly, miR-196a could inverse the tumor suppressive effects of Linc00472 in CRC, suggesting Linc00472 suppressed CRC progression, at least in part, through directly inhibiting miR-196a." (PMID 29930217, 2018). "Furthermore, a series of rescue experiments were designed and performed with results highlighting the capability of overexpressed LINC00472 to function as a tumor suppressor due to inhibition of TNBC cell proliferation, migration and invasion as well as tumor growth and metastasis." (PMID 33668040, 2021).
cancer (9 papers, 2010 to 2025). A tumor composed of atypical neoplastic, often pleomorphic cells that invade other tissues. "In addition, we found that the level of LINC00472 decreased gradually with the progress of cancer stage." (PMID 36371410, 2022). "However, LINC00472 may function as a mediator for various signaling pathways in different human cancers." (PMID 33668040, 2021). "As we predicted that FOXO3 was a target of miR‐23a‐3p and LINC00472 could bind to miR‐23a‐3p based on the bioinformatic analysis, we speculated the functionality of LINC00472 as a ceRNA of miR‐23a‐3p to regulate FOXO3 and subsequently influence BID‐dependent cancer cell apoptosis." (PMID 34363438, 2021).
LINC00472 also shares sentences with these, for which no sentence is quoted: hepatocellular carcinoma (2 papers); asthma (1); atrial fibrillation (1); liver cancer (1); non-small cell lung carcinoma (1); oral squamous cell carcinoma (1); osteosarcoma (1); prostate carcinoma (1).